EGFR (epidermal growth factor receptor)
Diseases named in the same sentence as EGFR in open-access papers (continued):
Sharing a sentence is not in itself a finding about the gene and the disease.
pulmonary fibrosis (continued). "The clinical features of lung injury induced by EGFR-TKI were identified as pre-existing pulmonary fibrosis, poor PS, and previous thoracic radiation, which were found to be independent risk factors in Japanese NSCLC patients." (PMID 33466795, 2021). "Gefitinib, a TKI used for the first-line treatment of EGFR-mutated NSCLC for almost two decades, is known to aggravate pulmonary fibrosis inflicted by bleomycin." (PMID 34063231, 2021). "Preclinically, a murine model of bleomycin-induced pulmonary fibrosis has been employed for detecting the effect of EGFR-TKIs in pulmonary tissue." (PMID 33466795, 2021). "An HRCT of the chest should be obtained before the initiation of EGFR-TKI therapy because pre-existing pulmonary abnormalities, such as lung fibrosis, are associated with an increased risk of ILD." (PMID 33466795, 2021). "Overexpression of EGF receptor in bronchial epithelium and type 2 pneumocytes of IPF patients.EGFR inhibition by gefitinib results in development of pulmonary fibrosis." (PMID 33562816, 2021). "The NSCLC patients with EGFR-TKI-induced lung injury had characteristic clinical profiles of risk factors, including smoking history, male sex, and pre-existing lung fibrosis." (PMID 33466795, 2021). "Experimental studies show increased TNF-α and EGFR expression in bleomycin-lung fibrosis as well as following exposure of the lungs to asbestosis." (PMID 32850151, 2020). "After in vivo and in vitro evaluations, we revealed that PEI from CBPP, as a lead compound, can improve lung function and alleviate pulmonary fibrosis by acting on the EGFR and MLC2 signaling pathways." (PMID 31333459, 2019). "Another mechanism involved in pulmonary fibrosis is the activation of the epidermal growth factor receptor (EGFR)." (PMID 29849916, 2018). "EGFR has been found to be upregulated in the lung tissues of patients and rodents with pulmonary fibrosis." (PMID 29849916, 2018). "Extensive evidence indicated that the MAPK pathway was the downstream signaling cascade of EGFR, which participated in the development of pulmonary fibrosis." (PMID 29849916, 2018). "EGFR plays an important role in alveolarization and lung fibrosis, but the length of time after exposure (6 and 24 hours) is too short to evaluate these effects in this gestation for sheep." (PMID 30005089, 2018). "Our present data implied that gefitinib inhibited pulmonary fibrosis in vivo through HMGB1/NOXs-ROS/EGFR-ERK/JNK/P38 pathways." (PMID 29849916, 2018). "Rapamycin prevents and inhibits progression of ongoing pulmonary fibrosis caused by expression of TGF−α and increased epidermal growth factor receptor (EGFR) signaling." (PMID 29703175, 2018). "Based on these findings, we concluded that metformin decreased EGFR-TKI-induced pulmonary fibrosis in vitro." (PMID 26497205, 2015). "We thus provide a rationale and experimental evidence for using metformin to attenuate pulmonary fibrosis that is induced by EGFR-TKIs." (PMID 26497205, 2015). "Taken together, these data suggest a protective role of metformin in attenuating EGFR-TKI-induced exacerbation of pulmonary fibrosis in vivo." (PMID 26497205, 2015). "Given that metformin significantly decreased activation of the TGF-β signaling pathway, and attenuated TGF-β-induced pulmonary fibrosis, we concluded that metformin attenuated EGFR-TKI-induced pulmonary fibrosis by inhibiting the TGF-β signaling pathway." (PMID 26497205, 2015). "In summary, we have shown that metformin attenuated EGFR-TKI-induced pulmonary fibrosis both in vitro and in vivo by inhibiting the TGF-β signaling pathway." (PMID 26497205, 2015). "Immunohistochemistry staining and qRT-PCR were utilized to determine the EGFR expression profile, both in protein and mRNA level, in patients with three different forms of lung fibrosis." (PMID 23841084, 2013). "To further implicate EGFR upregulation in lung fibrosis we investigated the mRNA expression levels of type I collagen (COL1A2) in different types of IIPs." (PMID 23841084, 2013).
pulmonary fibrosis (continued). "More studies are needed to delineate the role of EGFR in the pathogenetic cascade of abnormal wound repair leading to lung scarring and highlight potential benefits of EGFR as a therapeutic target for pulmonary fibrosis." (PMID 23841084, 2013). "Because IL-6 has been linked to the development of acute interstitial pneumonia, we expected that EGFR-TKI treatment-induced IL-6 production in cancer cells resulted in lung fibrosis." (PMID 23592411, 2013). "Secondly, our study was not designed to delineate mechanistic issues and elucidate the exact role of EGFR in different forms of lung fibrosis." (PMID 23841084, 2013). "Eight (16.7%) out of the 48 patients with preexisting pulmonary fibrosis developed EGFR-TKIs induced ILD." (PMID 21791074, 2011). "A risk-benefit analysis and patient selection should be considered as well as close monitoring of serum levels of KL-6, particularly if using EGFR-TKIs in patients with preexisting pulmonary fibrosis." (PMID 21791074, 2011). "Elevated expression of TGF-β1 may promote the progression of pulmonary fibrosis by activating the epidermal growth factor receptor (EGFR) pathway." (PMID 39457053, 2024). "Notably, all patients with a history of pulmonary TB, pulmonary fibrosis, and cancer in another body site had adenocarcinoma with EGFR Exon 19 deletion." (PMID 39429333, 2024). "The activation of EGFR signaling leads to lung fibrosis after SARS coronavirus infection." (PMID 35832075, 2022). "Similarly, epidermal growth factor receptor (EGRF) in animal models to study the development of SARS-CoV-induced fibrosis, evidence that pulmonary fibrosis is caused by a hyperactive host response to lung injury mediated by EGFR signaling." (PMID 36388923, 2022). "EGFR not only regulates pulmonary fibrosis, but also regulates bone structural integrity." (PMID 36307516, 2022). "EGFR+ SSc fibroblasts also expressed higher levels of interferon inducible genes (IFI27, BST2), which have been shown to correlate with SSc disease severity, and IL6, a profibrotic cytokine whose inhibition slows SSc-associated lung fibrosis." (PMID 36490328, 2022). "However, clinical studies of broadly acting tyrosine kinase inhibitors for treatment of skin and lung fibrosis have been marred by the development of serious adverse events and EGFR inhibition can paradoxically induce pulmonary fibrosis in patients and mice." (PMID 36490328, 2022). "Severe acute respiratory syndrome coronavirus (SARS-CoV) infection leads to the upregulation of EGFR ligands such as heparin-binding EGF-like growth factor (HB-EGF) and amphiregulin (AREG), and overactivation of EGFR leads to severe lung damage and pulmonary fibrosis." (PMID 34517756, 2021). "On the other hand, it is also involved in pulmonary fibrosis as a ligand of epidermal growth factor receptor (EGFR) and may contribute to complications in the lower airway." (PMID 31461941, 2019). "The phosphorylation of AKTS473 is regulated by EGFR, and it is a biomarker in pulmonary fibrosis." (PMID 31333459, 2019). "Interestingly, SARS-CoV infection in the context of overactive EGFR results in pulmonary fibrosis, supporting the idea that EGFR signaling supports tissue regrowth during respiratory infection." (PMID 31616667, 2019). "Thus, acting on the EGFR/PI3K/AKT signaling pathway is essential for the treatment of pulmonary fibrosis in COPD." (PMID 31333459, 2019). "Our evidence that an EGFR–RAS–ERK–ZEB1 axis may contribute to the early stages of lung fibrosis suggests that inhibiting EGFR signalling may be of clinical relevance for regulating human fibrotic lung disease." (PMID 30050057, 2019). "EGF is a ligand for EGFR, and activation of EGFR is related to pulmonary fibrosis in lung disease." (PMID 31333459, 2019). "Moreover, the activation of the PI3K/Akt signaling pathway was regulated by EGFR-induced pulmonary fibrosis." (PMID 31333459, 2019).
pulmonary fibrosis (continued). "In order to overcome such resistance, a combination of target therapy against both EGFR and MEK is indicated and similar combination against EGFR and c-Met was also addressed in patients with lung fibrosis and who are expressing abundantly type I collagen in the tumor mass." (PMID 29932172, 2018). "Second, we found that gefitinib was effective in reducing pulmonary fibrosis in mice, which might be associated with the HMGB1/NOXs-ROS/EGFR-MAPKs-AP-1/NF-κB signal." (PMID 29849916, 2018). "The present study suggested that gefitinib could alleviate lung fibrosis through the HMGB1/NOXs-ROS/EGFR-MAPKs-AP-1/NF-κB signal in bleomycin-induced pulmonary fibrosis." (PMID 29849916, 2018). "Other cancer drugs can lead to pulmonary fibrosis, like bleomycin, taxanes, and biological agents like epidermal growth factor receptor (EGFR) small-molecule tyrosine kinase inhibitors (TKIs), monoclonal antibodies to VEGF, and mammalian target of rapamycin (mTOR) inhibitors." (PMID 26904333, 2016). "We next tested the possibility of whether metformin attenuates EGFR-TKI-induced exacerbation of pulmonary fibrosis." (PMID 26497205, 2015). "The present findings may serve as a potential approach to preventing incidences of ILD and pulmonary fibrosis induced by EGFR tyrosine kinase inhibitors, such as gefitinib and erlotinib." (PMID 26288223, 2015). "We next asked whether metformin decreased EGFR-TKI-induced pulmonary fibrosis by inhibiting the TGF-β signaling pathway." (PMID 26497205, 2015). "Furthermore, the role of TGF-β in EGFR-TKI-induced pulmonary fibrosis was determined using a TGF-β mAb." (PMID 26497205, 2015). "Our results suggested that IL-6 secreted from EGFR-TKI-treated cancer cells induced lung fibrosis." (PMID 23592411, 2013). "Therefore, it seems plausible that both AREG and CTGF may be required to optimally activate the EGFR/TGF-β-mediated pulmonary fibrosis pathways." (PMID 40868999, 2025). "This gives hope that EGFR-targeted therapy may have good results in patient’s lung fibrosis." (PMID 39062713, 2024). "Moreover, further studies are needed to determine whether avitinib affects other signalling pathways related to pulmonary fibrosis, such as the recognized targets of EGFR and BTK." (PMID 36949426, 2023). "Thus, EGFR+ SSc fibroblasts, but not pericytes, express multiple pathologic signature genes associated with SSc skin and lung fibrosis." (PMID 36490328, 2022). "In addition, excessive activation of EGFR plays a role in the development of pulmonary fibrosis." (PMID 36353282, 2022). "So we hypothesized that fibroblast-specific p-EGFR mediated lung fibrosis." (PMID 35551173, 2022). "Furthermore, EGFR overexpression facilitates pulmonary fibrosis for a SARS-CoV-infected patient." (PMID 34063231, 2021). "In addition, based on the potentially pivotal role that dysregulation of AREG and EGFR signaling may play in pulmonary fibrosis pathogenesis, AREG could be a potential therapeutic target for IIM-related ILD." (PMID 34442026, 2021). "In addition to the potential role of metformin to prevent EGFR-TKI-induced pulmonary fibrosis, it may simultaneously enhance the anti-tumor effect of EGFR-TKI." (PMID 26497205, 2015). "To provide additional evidence that EGFR overexpression may contribute to the development and/or progression of pulmonary fibrosis we sought to correlate EGFR quantitative mRNA expression levels assessed by PCR analysis with functional parameters of disease severity, including FVC and DLCO." (PMID 23841084, 2013). "Although an assessment of pulmonary comorbidities, especially ILDs, is important to decrease the incidence of ILD induced by chemotherapy, the frequency of EGFR mutation in patients with pulmonary fibrosis and the clinical feature of these patients are not clear." (PMID 22191026, 2011). "Phosphorylated EGFR and p-AKT are apparently elevated in the myofibroblasts of idiopathic pulmonary fibrosis patients." (PMID 40612681, 2025).
pulmonary fibrosis (continued). "The core targets actively interact with major pathways in pulmonary fibrosis, including TNF, HIF-1, FOXO, AGE-RAGE, PD-L1 expression, VEGF, IL-17, relaxin, ErbB, and EGFR tyrosine kinase inhibitor resistance pathways." (PMID 41361355, 2025). "Among the 24 patients with EGFR-TK positivity, 12.5% had a history of pulmonary TB, 16.7% had active COPD, 16.7% had pulmonary fibrosis, and 4.2% had cancer in another body site." (PMID 39429333, 2024). "Pulmonary fibrosis is seen in individuals infected with SARS-CoV 2 and is believed to be mediated by the epidermal growth factor receptor (EGFR) signaling pathway." (PMID 38932130, 2024). "Pulmonary fibrosis has been reported in individuals infected with SARS-CoV, and this fibrotic process is mediated by the EGFR signaling pathway." (PMID 37626956, 2023). "A total of 49 active ingredients were analyzed and screened in Cephalus cephalusis, including 35 pulmonary fibrosis targets, and 10 key targets such as ALB, EGFR were screened after software analysis." (PMID 37713849, 2023). "However, it is unknown whether metformin attenuates EGFR-TKI-induced pulmonary fibrosis." (PMID 26497205, 2015). "Metformin can also be used in combination with EGFR-TKIs in selected NSCLC patients to increase the efficacy of TKIs and in an attempt to prevent the potential side-effect of pulmonary fibrosis." (PMID 26497205, 2015). "AREG also participates in pulmonary fibrosis by modulation of TGF-α, and EGFR inhibitors can decrease pulmonary fibrosis." (PMID 24788984, 2014). "Given that TGF-β is a multifunctional cytokine that drives inflammation and pulmonary fibrosis, we hypothesized that anti-TGF-β might reduce immune pneumonia and fibrosis induced by anti-PD-1 and EGFR-TKI treatment." (PMID 39004699, 2024). "It is possible that bleomycin is not able to induce typical type 2 immune response–mediated lung fibrosis, or that ILC2s contribute to fibrosis development through other pathways, including the EGFR pathway that was investigated above." (PMID 39405112, 2024). "Previous studies have demonstrated that targeting EGFR and BTK may be an effective method to mediate the development of pulmonary fibrosis." (PMID 36949426, 2023). "Inhibition of AREG or EGFR in TGF-β1-stimulated lung fibroblasts diminished AREG-dependent fibroblast proliferation, expression of α-smooth muscle actin and collagen, strongly suggesting a role of EGFR/ADAM17/AREG signaling in pulmonary fibrosis in vivo." (PMID 29540993, 2018). "Gefitinib, an EGFR-tyrosine kinase inhibitor (EGFR-TKI), has the ability to inhibit fibroblast proliferation, therefore lessening the collagen and extracellular matrix (ECM) deposition in pulmonary fibrosis." (PMID 29849916, 2018). "Taken together, the findings from the current study suggested that metformin might be a promising agent to protect against the side-effects of EGFR-TKI, and may block pulmonary fibrosis." (PMID 26497205, 2015). "The effect of metformin on EGFR-TKI-induced exacerbation of pulmonary fibrosis was examined in vitro and in vivo using MTT, Ki67 incorporation assay, flow cytometry, immunostaining, Western blot analysis, and a bleomycin-induced pulmonary fibrosis rat model." (PMID 26497205, 2015). "The aim of our study was to investigate the expression profiles of EGFR in three forms of IIPs, including idiopathic pulmonary fibrosis (IPF), cryptogenic organizing pneumonia (COP), and nonspecific interstitial pneumonia (NSIP)." (PMID 23841084, 2013). "In addition, EGFR-TKI can induce chronic inflammation in alveolar and bronchial epithelia, promote the migration and proliferation of fibroblasts, and stimulate the production of extracellular matrix, ultimately resulting in pulmonary fibrosis." (PMID 40538542, 2025). "However, EGFR-TKIs have been found to suppress HSP-70 expression in the lungs, which may potentially promote pulmonary fibrosis." (PMID 38895622, 2024).
pulmonary fibrosis (continued). "In this study, we explored the roles of Hif-1α and its downstream molecule EGFR in pulmonary fibrosis mice and the APD group, suggesting that APD might regulate ferroptosis by inhibiting the Hif-1α-EGFR pathway, thereby alleviating pulmonary fibrosis." (PMID 38584671, 2024). "EGFR activation also leads to STAT3 phosphorylation, which can induce inflammatory responses and imbalanced anti-virus adaptive immune responses, inhibit anti-virus interferon responses, and promote M2 macrophage polarization, pulmonary fibrosis, and thrombosis." (PMID 36532549, 2022). "Third, the expression and activation of EGFR in different breeds of rodents and their responses to different doses of gefitinib had direct effects on the MAPK signals which could promote or inhibit pulmonary fibrosis." (PMID 29849916, 2018).